EZR (ezrin)
Diseases named in the same sentence as EZR in open-access papers (continued):
Sharing a sentence is not in itself a finding about the gene and the disease.
cancer (continued). "Ezrin, a member of the ezrin–radixin–moesin protein family, is strongly expressed in many types of cancers." (PMID 36156321, 2023). "Activated ezrin regulates key events in a variety of cancers and interacts with different proteins to participate in different signaling pathways." (PMID 37328063, 2023). "The interaction of ezrin with F-actin has been significantly studied in the cancer setting, where ezrin is thought to facilitate cancer cell motility and invasion." (PMID 36899847, 2023). "Ezrin has become a promising therapeutic target in reducing the metastatic burden of several cancer types." (PMID 37371090, 2023). "Ezrin mediates cell growth and survival through Akt signaling in some cancers, which is essential for cancer proliferation, invasion, migration, and survival." (PMID 37328063, 2023). "Following EMT, Ezrin can further enhance cancer cell invasion and migration by facilitating cytoskeleton remodeling, increasing cell motility, as well as polarizing macrophages towards the M2 type." (PMID 37371090, 2023). "Ezrin, being an adapter protein between the actin cytoskeleton and the plasma membrane, is involved in cancer promotion through the modulation of signaling pathways." (PMID 37373333, 2023). "Ezrin regulates cancer-cell survival and metastatic cascade by controlling cytoskeletal remodelling and cellular signalling pathways." (PMID 37629086, 2023). "The protein ezrin has been shown to enhance cancer cell motility and invasion leading to malignant behaviours in solid tumours, but a similar regulatory function in the early physiological reproduction state is, however, much less clear." (PMID 36899847, 2023). "Ezrin promotes pro-survival signaling, particularly in disseminated cancer cells, to facilitate metastatic outgrowth." (PMID 36923551, 2022). "Ezrin is essential for cancer progression, acting as a scaffolding protein and interacting with related proteins in cancer cells." (PMID 36355541, 2022). "The ERM proteins, especially ezrin, also directly bind to the P-glycoprotein (P-gp), which is a key player in multidrug-resistant phenotypes in cancer." (PMID 35328667, 2022). "We recently utilized one of these inhibitors, NSC668394 (NSC), which preferentially binds to and inhibits ezrin activity over other ERMs and showed that it reduced ezrin activity in vitro and attenuated cancer cell migration and lymph node metastasis in vivo." (PMID 36923551, 2022). "Small molecule inhibitors of ezrin have been developed and investigated as candidate molecules that suppress cancer metastasis." (PMID 35328667, 2022). "In pancreatic ductal adenocarcinoma (PDAC), the level of ezrin in CSCs is significantly higher than that in normal cancer cells." (PMID 36355541, 2022). "The increased expression of ezrin leads to increased malignancy and decreased survival in aggressive cancers." (PMID 36355541, 2022). "Ezrin is also known to regulate survival signaling, particularly in disseminated cancer cells to facilitate metastatic seeding and outgrowth in distant organ sites." (PMID 36923551, 2022). "While some functional redundancy exists among ERM proteins, studies have highlighted distinct but complementary roles for ERMs in regulating the same cellular processes, such as ezrin and moesin in cancer cell invasion." (PMID 36923551, 2022). "Nonetheless, studies have demonstrated the ability of ezrin to promote drug resistance in both solid and blood-based cancers through different mechanisms." (PMID 36923551, 2022). "In cancer cells, the relative membrane localization of EZR is increased, which facilitates the process of cancer progression and invasion." (PMID 36553191, 2022). "Ezrin is a cytoskeletal organizer that promotes metastasis in many cancer types by reorganizing the cytoskeleton or controlling the signal transduction [e.g., activating NF-κB, epithelial–mesenchymal transformation (EMT), and AKT pathways]." (PMID 34485151, 2021).
cancer (continued). "Clustering of VCAM-1 on the cell surface, acting through Ezrin, triggers Akt activation and protects cancer cells from proapoptotic cytokines such as the TNF-related apoptosis-inducing ligand (TRAIL)." (PMID 33816243, 2021). "Accumulated evidence suggests that ezrin serves as a scaffold protein for some drug transporters and certain cancer-related proteins, including EGFR2 and several receptor kinases." (PMID 34577118, 2021). "Another protein involved in cytoskeleton reorganization during EMT and cancer progression is ezrin, which is involved in cytoskeleton–plasma membrane–extracellular matrix mechanical signaling." (PMID 34198671, 2021). "Meanwhile, EZR participated in the regulation of adhesion molecules and signal pathways involved in the migration and invasion cancer cells." (PMID 34627255, 2021). "In recent years, researchers have confirmed that EZR is involved in cellular interaction by adopting adhesion molecules such as Rac1/RhoA and eventually regulate the invasion and metastasis of cancers, and PI3K/Akt signal pathways." (PMID 34627255, 2021). "Ezrin has been shown to promote cell migration and invasion in several types of cancer where high protein expression has been correlated with poor patient prognosis." (PMID 33946771, 2021). "Overexpression of ERBB3, EZR, and TM9SF2 has been associated with cancer progression, increased proliferation and metastasis or poor survival." (PMID 33690729, 2021). "It has been described that while in normal tissue ezrin is correlated with a membranous expression, its cytoplasmic presence increases in cancer, and this is consistent with our results." (PMID 34198671, 2021). "Activated Ezrin regulates key events and interacts with different proteins in a variety of cancer types." (PMID 33240887, 2020). "Since cell differentiation is considered one of the possible ways to contain cancer propagation, ezrin appears a promising target for the treatment of NB." (PMID 33326488, 2020). "Our results confirmed the pivotal role of Ezrin in regulating cell migration and invasion, and indicate this protein as a potential target for new anti-cancer therapeutic approaches." (PMID 33003361, 2020). "The effect of enhanced Ezrin proteins in cancer metastasis takes different forms in various cancers." (PMID 33240887, 2020). "In this review, we summarized not only the oncogenic roles of Ezrin but also its pathophysiological roles and potential pharmacological regulators in a wide range of cancer types." (PMID 33240887, 2020). "High levels of Ezrin are observed in many cancers with lung metastasis, indicating poor survival and bad prognoses." (PMID 33240887, 2020). "In cancer cells, Ezrin is significantly activated, phosphorylated, and elevated, enhancing cancer cells’ invasive abilities." (PMID 33240887, 2020). "Specifically EZR is a cytoplasmic peripheral membrane protein, which plays a key role in cell surface structure adhesion, migration and organization of various human cancers, including NSCLC." (PMID 32545325, 2020). "Given the key role played by Ezrin in the regulation of actin cytoskeleton organization, we thoroughly investigated the ability of the two diterpenes to interact with this protein in cancer cells." (PMID 33003361, 2020). "In order to draw a most recent conclusion from the up-to-date work, below we summarized the specific roles of Ezrin in various cancers, highlighting the special signaling cascades and pathophysiological roles." (PMID 33240887, 2020). "Ezrin links the cytoskeleton to cell surface integrins and plasma membrane receptors, contributing to the proliferative and metastatic potential of cancer cells." (PMID 33086476, 2020). "Pharmacological inhibition of Ezrin has significantly reduced cancer cell migration and invasion into the lymph nodes and lungs in vivo in real time." (PMID 33240887, 2020).
cancer (continued). "Over the past decade, many studies have attempted to develop targeted cancer treatment strategies using small molecule inhibitors of Ezrin." (PMID 33240887, 2020). "Surprisingly, although Ezrin showed widely pro-metastatic capacity in many cancers, the anti-metastatic effect of its inhibitors was only seen in a few cancer types." (PMID 33240887, 2020). "Because of ezrin’s ability to modulate actin dynamics and promote metastasis in in vivo models of various cancers, small molecule inhibitors have been developed to target ezrin." (PMID 33066583, 2020). "Despite various downstream pathways of Ezrin been identified in cancers, it is expected that identification of small molecule inhibitors of Ezrin would lead to the discovery of anti-metastatic and anti-invasion drugs." (PMID 33240887, 2020). "During cancer development, the relative membrane localization of Ezrin proteins is increased and cell–cell contact is disrupted." (PMID 33240887, 2020). "Together, our results highlight the importance of phosphorylated ezrin as a biomarker for cancer metastasis diagnosis." (PMID 31936668, 2020). "Here by reviewing recent findings across a wide spectrum of cancer types we will highlight the structures, protein interactions and oncogenic roles of Ezrin as well as the emerging therapeutic agents targeting Ezrin." (PMID 33240887, 2020). "Here, we investigated the effect of cancer cell-derived CM on macrophage differentiation and on the role of ezrin in this process." (PMID 33086476, 2020). "The data presented here, to our knowledge, are the first to show that pharmacological inhibition of ezrin can effectively impede migratory capacity of cancer cells in vivo and reduce metastatic burden in LNs and lungs in BC models." (PMID 30678714, 2019). "Ezrin is recognised as having a proactive role in cancer metastasis through control of its phosphorylation status, often by diminished phosphatase activity." (PMID 31382374, 2019). "To study the effect of ezrin inhibition on cancer cells in vivo, we have developed a novel intravital model using a lymphatic reporter mouse to directly track cancer cell migration within lymph node metastatic nodules." (PMID 30678714, 2019). "When histology of different carcinomas is correlated with benign FA with respect to phospho-ezrin, we observed that the marker was highly significant (p = 0.0001)." (PMID 30996241, 2019). "Reduced expression of ezrin can inhibit metastasis of cancer cells in several murine and human cancer models." (PMID 30285121, 2018). "In the cancer model, acute perturbation of the ezrin/NHERF1 interaction had greater effects on nuclear roundness scores and nuclear area, possibly in association with intrinsic unidentified mutations." (PMID 29520890, 2018). "Ezrin also takes part in several signaling pathways, such as Wnt/β-catenin, PI3K/Akt and CD44, all of which are associated with cancer progression." (PMID 29190988, 2017). "In aggregate, these functions suggest that Ezrin plays a pivotal role in the development and progression of cancer." (PMID 29190988, 2017). "Thirdly, the phosphorylation of Ezrin is important in cancer development, but the included studies only evaluated a simple expression of Ezrin." (PMID 29190988, 2017). "Its association with malignant behavior has been suggested in several experimental models, and in several cancers strong ezrin expression correlates with inferior outcome." (PMID 28953975, 2017). "A correlation appears to exist between high levels of ezrin expression in highly invasive cancer cells and low levels of ezrin expression in low-invasive cancer cells." (PMID 28061797, 2017). "Ezrin and p130Cas are structural proteins with an important role in signaling pathways and have been shown to promote cancer dissemination." (PMID 27622508, 2016). "We observed the role of Ezrin in cancer cell invasion by chorioallantoic membrane (CAM) invasion assay using hematoxylin and eosin (H & E) and IF staining." (PMID 26933912, 2016).
cancer (continued). "Increasing evidence indicates an important role for Ezrin in the development and progression of malignant tumors." (PMID 26933912, 2016). "Ezrin has been shown to promote cancer dissemination by several mechanisms including changes in signaling, increased cell motility and the ability to survive anoikis, invade and proliferate in 3-dimensional environment." (PMID 27622508, 2016). "Ezrin overexpression has been shown in other cancer such as pancreatic carcinoma, rhabdomyosarcoma and osteosarcoma." (PMID 26983550, 2016). "Our collaborators had initially shown that intracellular distribution of proteins can act as a marker or predictor for development of certain cancers, though ezrin’s cytoplasmic expression proved to be significant, willin’s distribution did not." (PMID 27438856, 2016). "Over-expression of Ezrin protein enhanced the metastatic potential of a variety of tumors including carcinomas of the endometrium and pancreas." (PMID 26933912, 2016). "In terms of the limits of the single study, as well as in order to better understanding the significance of Ezrin expression in the prognosis of cancer patients, performing a comprehensive meta-analysis to evaluate the published studies is necessary." (PMID 26632332, 2015). "In this report, the overexpression of Dsg3 enhanced phosphorylation and localisation of Ezrin at basal plasma membrane domains, events indicative of the aberrant regulation of Ezrin in cancer progression." (PMID 25629808, 2015). "Ezrin is a membrane-cytoskeleton linker protein involved in growth regulating and metastatic behaviour of cancer cells." (PMID 25613038, 2015). "Altered expression, phosphorylation and sub-cellular localisation of Ezrin is also correlating with enhanced migration, invasion and metastasis in a variety of cancers." (PMID 25629808, 2015). "In view of this, we performed this updated meta-analysis including 44 articles with 55 studies and elucidated that the high Ezrin expression was significantly associated with poor OS, DFS and DSS/MFS in cancer patients." (PMID 26632332, 2015). "Interaction of CD44 with growth factor receptors stimulates the proliferation and invasion of cancer cells; however, its interaction with ezrin/radixin/moesin proteins activates the tumor suppressor, merlin, to inhibit cancer growth." (PMID 26572077, 2015). "Although both AKAP12 and Ezrin seem to inhibit proliferation, as outlined in detail above Ezrin, seems to change its function in cancer." (PMID 26202611, 2015). "Ezrin (EZR) and Podocalyxin (PODXL) are proteins associated with invasion, migration and poor prognosis in various types of cancer." (PMID 26135398, 2015). "In the present meta-analysis, the aim is to assess the correlation between Ezrin expression and the survival outcomes in cancer patients via collecting global related literatures to carry out a systematic analysis." (PMID 26632332, 2015). "Ezrin is expressed in a variety of cancers and the prognostic value of ezrin expression seems to differ in different cancer forms." (PMID 24885195, 2014). "It is reported that ezrin expression is correlated with metastasis and poor prognosis of many cancers such as nonsmall cell lung cancer, breast cancer, and gastric adenocarcinoma." (PMID 25136657, 2014). "In other cancers, miR-183 has also been demonstrated to reduce metastasis through its action on Ezrin." (PMID 25593998, 2014). "The expression of ezrin, a membrane cytoskeletal crosslinker and Src substrate, correlates with poor outcome in a diversity of cancers including breast." (PMID 25231728, 2014). "We and others have previously shown an intrinsic regulatory role for ezrin in cancer invasion and metastasis." (PMID 25231728, 2014). "In the cancer tissues, ezrin was mainly expressed in the cytoplasm adjacent to the cell membrane, with few observed on the cell membrane." (PMID 24959233, 2014).
cancer (continued). "It has also been demonstrated that over-expression of miR-183 inhibits migration of cancer cells through its action on VIL2 / Ezrin." (PMID 25593998, 2014). "Previous studies have shown that expression of ezrin, a member of the ERM (ezrin-radixin-moesin) cytoskeleton-associated protein family, is correlated with poor outcome in many types of human cancers." (PMID 25580109, 2014). "The present study adds ezrin in its T567 phosphorylated state as an important player in the understanding the molecular mechanisms behind the cancer invasive process." (PMID 24086451, 2013). "Ezrin is known to be essential for many fundamental cellular processes and is also related to the malignant behavior of various malignant tumors." (PMID 23357878, 2013). "We observed that ezrin depletion decreased cancer cell motility and invasiveness and inhibited podia formation." (PMID 23357878, 2013). "The present study adds ezrin in its T567 phosphorylated state as an important player in the race for understanding the molecular mechanisms behind the cancer invasive process." (PMID 24086451, 2013). "Of note, Ezrin expression levels are elevated in human CRC cancer cells, compared to normal tissues." (PMID 23755307, 2013). "Recent studies suggest that the Ezrin protein is correlated with the metastatic potential of several malignant tumors." (PMID 22922800, 2012). "High expression of the Ezrin protein has been reported to correlate with the metastatic potential of several malignant tumors." (PMID 22922800, 2012). "Fascin-1, ezrin and paxillin are regulated by microRNAs and take part in the modulation of malignant progression in carcinoma." (PMID 23209815, 2012). "Previous studies have implicated Ezrin in coordinating signaling complexes on membranes in cancer, raising the question of whether the Ezrin-mediated control of autophagy may be attributed to an alteration of signaling pathways." (PMID 39937579, 2025). "E2 has been reported to rapidly promote the phosphorylation of the ezrin protein through GPER or ERβ, causing ezrin-dependent rearrangement of the cytoskeleton and F-actin remodeling, which stimulates the migration and invasion of ERα-negative cancer cells." (PMID 38476263, 2024). "The role of increased ezrin in cancer metastasis varies between different cancer types." (PMID 39791707, 2024). "The results from Zhao's study also suggested that Ezrin may have pro-angiogenic properties in cancer development." (PMID 38577590, 2024). "The results implicate that targeting radixin and ezrin may facilitate finding novel treatments for colorectal and other types of cancers." (PMID 39457653, 2024). "Overexpression of ezrin in cancer is presumably through transcriptional and/or epigenetic alterations, as no activating mutations for ezrin, to our knowledge, have been identified." (PMID 36938826, 2023). "Given this, Ezrin represents a promising therapeutic target for cancer patients." (PMID 37371090, 2023). "Knockout of ezrin prevented enhanced cancer cell migration by PALM2 overexpression." (PMID 37328063, 2023). "In summary, prenylated PALM2 enhances the migration of cancer cells by activating ezrin." (PMID 37328063, 2023). "With their overexpression in highly metastatic cancers, direct interaction between these proteins and S100P-mediated Ezrin activation may have a more prominent prometastatic role." (PMID 37371090, 2023). "Given the importance of ezrin expression and Thr567 phosphorylation as key regulators of cellular motility and cancer metastasis, we sought to determine whether ezrin could equally contribute to cellular motility and invasion in the context of EVT cells." (PMID 36899847, 2023). "Recent studies have found that ezrin participates in the invasion and metastasis of cancer cells." (PMID 37248251, 2023). "Furthermore, ezrin has been shown, at least in cancer cells, to regulate the number and size of focal adhesion when affecting their migration/invasion." (PMID 36899847, 2023).